SLC1A3 (solute carrier family 1 member 3)
Diseases named in the same sentence as SLC1A3 in open-access papers (continued):
Sharing a sentence is not in itself a finding about the gene and the disease.
cancer (24 papers, 2014 to 2026). A tumor composed of atypical neoplastic, often pleomorphic cells that invade other tissues. "In addition, its suppression was found to be associated with cancer cell cycle arrest and apoptosis, and in vivo experiments revealed that SLC1A3 upregulation enhanced metastasis and tumor growth." (PMID 38705513, 2024). "In the following analysis, we will focus on SLC1A3, a glutamate transporter, due to its significant correlation with PD-L1 expression and its potential role in cancer progression." (PMID 41234499, 2026). "In the stiff matrix of TME, ECM mechanotransduction re-localizes YAP/TAZ to the nucleus and activates the transcription of GLS1 and SLC1A3 in both cancer cells and CAFs." (PMID 38218942, 2024). "Pharmacologic blockade of SLC1A3 sensitizes cancer cells to electron transport chain inhibitors and induces cell death." (PMID 38886847, 2024). "Given that SLC1A3 is reduced in HCT116 ASNS−/− tumors, this favorably predisposes cancer cells, with reduced amino acid uptake to cell death by necrosis." (PMID 38886847, 2024). "The nine genes identified in our signature (Dhx9, Dusp12, Fhl1, Ifitm1, Ndufs1, Pja2, Slc1a3, Soga1, and Spon2) have each been investigated for their role in cancer." (PMID 38193115, 2024). "Consistently, treatment of L-asparaginase with the SLC1A3 pharmacological inhibitor TFB-TBOA effectively hinders cancer cell proliferation in vitro and in vivo." (PMID 35011702, 2022). "Here, we took a functional genetic approach and identified SLC1A3 as a novel contributor to ASNase resistance in cancer cells." (PMID 31523835, 2019). "Here, we demonstrate that ASNase stimulates aspartate and glutamate consumptions, and their refilling through SLC1A3 promotes cancer cell proliferation." (PMID 31523835, 2019). "Here, we described the identification of SLC1A3, an aspartate/glutamate transporter, as a novel contributor to ASNase resistance and metastasis in cancer cells." (PMID 31523835, 2019). "Altogether, using a genome‐wide functional genetic approach, we identified SLC1A3, an aspartate/glutamate transporter, as a key determinant in the survival of cancer cells during ASNase treatment." (PMID 31523835, 2019). "To determine the general role of SLC1A3 in the response to glutamine starvation, we examined a panel of cell lines derived from different cancer types." (PMID 30122553, 2018). "It is reported that L-theanine competitively inhibited the uptake of glutamate substrate through solute carrier family 1, member 3 (SLC1a3) and SLC1a2 expressed in cancer cells." (PMID 28812027, 2017). "The mechanism involved cannot be deduced from the present studies, yet it is notable that regulated nuclear localization of SLC1A3 (GLAST-1) in cancer cells has been reported independently by two groups." (PMID 25981639, 2015). "SLC1A3 in CAFs could provide aspartate to cancer cells, while cancer cells in turn secrete glutamine-derived glutamate through SLC1A3 to CAFs." (PMID 38218942, 2024). "SLC1A3 is also a downstream target for key proteins involved in cancer progression during hypoxia." (PMID 38705513, 2024). "Additionally, given the function of Slc1a3 involved in proliferation in cancer and stem cell have been reported, while Slc7a2 was rarely mentioned." (PMID 38203268, 2023). "Interestingly, one study showed that treatment with L-asparaginase in solid tumors enhances aspartate and glutamate consumption via SLC1A3, promoting cancer cell proliferation." (PMID 35011702, 2022). "Indeed, exogenous expression of gpASNase1, which converts intracellular asparagine to aspartate, or overexpression of the aspartate transporter SLC1A3, facilitating cancer cells to take up environmental aspartate, significantly increases tumor growth in vivo." (PMID 35011702, 2022).
cancer (continued). "SLC1A3 is an aspartate and glutamate transporter, and overexpression of SLC1A3 may promote cancer cell proliferation via “enhanced permeability” of aspartate and glutamate and fueling aspartate, glutamate and glutamine metabolisms." (PMID 35631480, 2022). "Accordingly, SLC1A3‐KO reduced aspartate uptake level only in SLC1A3‐expressing cancer cells." (PMID 31523835, 2019). "Interestingly, the sensitivity profiles of the tested cancer cell lines to ASNase treatment were generally consistent with the impact of SLC1A3‐KO on aspartate uptake, with the exception of BT549 cells." (PMID 31523835, 2019). "Slc1a3 is upregulated in actively cycling SCs of the skin interfollicular epidermis, hair follicles and sebaceous glands and plays a role in SC/progenitor cell activation and promotes cell proliferation and survival of cancer cells under conditions of nutrient starvation or hypoxia." (PMID 33199446, 2020). "Notably, we demonstrate that SLC1A3 inhibition in combination with ASNase treatment could hinder cancer cell proliferation by inducing either cell cycle arrest or apoptosis, which was observed in ALL cells following ASNase treatment." (PMID 31523835, 2019). "The authors demonstrated that cancer cell lines resistant to ETC inhibition maintain their aspartate level high using the SLC1A3 transporter, and modulation of SLC1A3 notably changed the sensitivity of cancer cells to ETC suppression." (PMID 38705513, 2024). "Some cancer cells have the ability to acquire aspartate from the environment via the expression of low- or high-affinity aspartate membrane transporters, such as SLC1A2 and SLC1A3, or via macropinocytosis." (PMID 34827664, 2021). "This is supported by our findings that both aspartate and glutamate could rescue ASNase toxicity in SLC1A3 KO or negative cancer cells." (PMID 31523835, 2019). "To interrogate the influence on differential gene expression profiles by SLC1A3 and ASNase, we performed transcriptome analysis in three cancer cell lines: PC3 (endogenous expression of SLC1A3), DU145 wild type (SLC1A3 negative), and DU145‐V5‐SLC1A3 (ectopic expression of SLC1A3)." (PMID 31523835, 2019). "Inhibitors of SLC1A3 that do not cross into the CNS, such as UCPH-101, may have efficacy in the inhibition of cancer growth without profound general toxicity." (PMID 30122553, 2018).
neurological disorders (8 papers, 2015 to 2025). "Genetic variation in SLC1A3 – the gene encoding EAAT1 - has been linked to several neurological disorders with partially overlapping clinical features." (PMID 29066757, 2017). "The SLC1 subfamily, specifically SLC1A3 (EAAT1), SLC1A2 (EAAT2), and SLC1A1 (EAAT3), are excitatory amino acid transporters that regulate glutamate concentrations in the synaptic cleft, making them important targets for neurological disorder therapeutics." (PMID 40308755, 2025).
infection (6 papers, 2016 to 2025). The state of being infected such as from the introduction of a foreign agent such as serum, vaccine, antigenic substance or organism. "Sodium voltage-gated channel alpha subunit 3 (SCN3A) and two solute carriers SLC24A2 and SLC1A3 were highly altered following infection." (PMID 29085037, 2017). "Enrichment of populations of astrocytes that upregulate inflammatory‐responsive genes such as Pvalb and Slc16a3 was observed, while astrocyte populations enriched for homeostatic glutamate transporter genes, such as Slc1a2 and Slc1a3, decreased over the course of infection." (PMID 40635167, 2025). "Sodium voltage-gated channel alpha subunit 3 (SCN3A) and two solute carriers SLC24A2 and SLC1A3 were highly altered following infection, indicating that ion transport could be important in response to infection." (PMID 29085037, 2017).
genetic diseases (1 paper, 2022). "The linkage of human genetic diseases to genes encoding EAAT1 (SLC1A3), EAAT2 (SLC1A2) and EAAT3 (SLC1A1) revealed additional roles of EAATs in cell and organ physiology." (PMID 33587237, 2022).
SLC1A3 also shares sentences with these, for which no sentence is quoted: glaucoma (19 papers); normal tension glaucoma (12); neurodegenerative disease (9); Parkinson disease (8); amyotrophic lateral sclerosis (7); ischemia (7); multiple sclerosis (7); Hyperglycemia (6); psychiatric disorder (5); Thiamine deficiency (5); Hyperammonemia (4); brain cancer (3); brain injury (3); brain tumors (3); Cerebral ischemia (3); retinal degeneration (3); retinal ischemia (3); Wernicke encephalopathy (3); age-related hearing loss (2); alcohol dependence (2); Brain atrophy (2); cerebellar ataxia (2); clear cell renal carcinoma (2); epileptic encephalopathies (2); fragile X-associated tremor/ataxia syndrome (2); frontotemporal dementia (2); Huntington disease (2); Insulin resistance (2); mastitis (2); multiple myeloma (2).
A further 67 diseases each share a sentence with SLC1A3 in 2 papers or fewer.